IDH2 (isocitrate dehydrogenase (NADP(+)) 2)
Diseases named in the same sentence as IDH2 in open-access papers (continued):
Sharing a sentence is not in itself a finding about the gene and the disease.
cancer (continued). "While mutations have been observed in IDH1 and IDH2, IDH3 mutations have not been found in cancer." (PMID 29342092, 2018). "Given that IDH2 also performs catalytic actions on isocitric acid, by dehydrogenating it to form α-ketoglutarate and NADPH, we speculate that cancer cells may themselves provide more NADPH and TCA cycle intermediates to maintain hypoxia survivability through G6PD and IDH2 pathways." (PMID 26956544, 2016). "Also, in contrast to IDH1 and IDH2, the heterotetrameric IDH3 is not subjected to cancer mutations." (PMID 29439493, 2018). "Kaplan-Meier analyses demonstrated that IDH2-mutant and triple negative SNCs have a more favorable DSS compared to NUT carcinoma (p = 0.014)." (PMID 36937407, 2023). "Due to the oxygen deprivation, mitochondrial aconitase, SDH, IDH2 and ATP5B dropped significantly in non-cancerous cells but remained stable or even increased in hypoxic cancer cells." (PMID 26956544, 2016).
hematologic malignancies (12 papers, 2018 to 2025). "AG-221 is currently being evaluated in several clinical trials for the use in advanced hematologic malignancies positive for a mutated IDH2." (PMID 30857299, 2019). "This IDH2 inhibitor underwent Phase I and Phase II clinical trials, in which effective 2HG levels decrease was observed both in bone marrow and in plasma, achieving sustainable remission of disease in some patients with advanced hematologic malignancies harbouring IDH2 mutations." (PMID 30356832, 2018). "Small molecule inhibitors targeting cellular oncoproteins and enzymes such as BCR-ABL, JAK2, Bruton tyrosine kinase, FLT3, BCL-2, IDH1, IDH2, are biomarker-driven chemotherapy-free agents approved for several major hematological malignancies." (PMID 33879198, 2021). "At present, AG-221 is being investigated in clinical trials for the therapy of patients with advanced IDH2-mut hematologic malignancies." (PMID 30857299, 2019). "Although solid tumors cells are believed to be more dependent on BCL-XL than hematologic malignancies, our results suggest that some AML cases, for example, BRCA2- or IDH2-mutated, may need this particular protein more than the other BCL2 family members for their survival." (PMID 34202143, 2021). "Moreover, AG-221 is a specific inhibitor of the IDH2 mutant, currently under phase I and II investigations, which is shown to reduce 2HG levels in plasma and bone marrow and induce durable remissions in patients with IDH2 mutant advanced hematologic malignancies." (PMID 31366176, 2019). "Among 39 patients with newly diagnosed mutant-IDH2 AML who received enasidenib monotherapy in this phase I/II trial, median age was 77 years (range 58–87) and 23 patients (59%) had had an antecedent hematologic disorder." (PMID 30967620, 2019).
CNS tumors (9 papers, 2013 to 2025). "To date, the most crucial molecular marker of tumors of the CNS is IDH1/IDH2 mutations, the identification of which is an essential component of the diagnosis, characterization, and prognosis of diffuse gliomas." (PMID 37568598, 2023). "Several follow-up studies encompassing thousands of central nervous system neoplasms have found similar frequencies of IDH1 and IDH2 mutations." (PMID 23847760, 2013). "The absence of IDH1 or IDH2 mutations is an essential characteristic of GBM as defined in the 2021 WHO classification of CNS tumors." (PMID 40336841, 2025). "Given the “glioblastoma IDH-wild-type” is defined by what it is lacking (i.e., lack of IDH1 and IDH2 hotspot mutations) rather than what it is harboring, many opportunities exist to identify new CNS tumor entities with unique genetic and epigenetic features within this HGG group." (PMID 39335555, 2024).
infection (8 papers, 2010 to 2025). The state of being infected such as from the introduction of a foreign agent such as serum, vaccine, antigenic substance or organism. "Specifically, GAPDH1, IDH2, and FAS1b were significantly downregulated by infection in both dietary groups, while GlyS59, Acsl3, and HADH1 were significantly downregulated only in the NO group." (PMID 41390792, 2025). "We confirmed that the mRNA expression of Mdh2 and Idh2 was altered post infection (P< 0.01)." (PMID 36618398, 2022). "Infection with M. tuberculosis produced a significant reduction in Idh2 in WT BMDM with no reduction in Sirt3−/− BMDM." (PMID 33531400, 2021). "We identified no less than 8 enzymes (ACO-2, F53F4.10, W02F12.5, FUM-1, IDH-2, SDHA-1, CTS-1, F23B12.5) that are part of the citric acid cycle which might reflect the need for extra energy whilst fighting off an infection." (PMID 20163716, 2010).
adenocarcinoma (6 papers, 2017 to 2024). A common cancer characterized by the presence of malignant glandular cells. "Multiregional analysis of an adenocarcinoma harboring two IDH2 mutations revealed parallel evolution originating from a KRAS‐mutated lineage, further supporting subclonal evolution promoted by IDH1/2 mutations." (PMID 32333643, 2020). "We observed a significant increase in CNA in FGFR3, BCL3, and IDH2 in CCNE1-amplified versus nonamplified EG adenocarcinoma." (PMID 38717153, 2024).
hematopoietic neoplasms (5 papers, 2018 to 2022). "Homozygous missense mutations in both IDH1 or IDH2 have been described in several cancer types, including glioma, cholangiocarcinoma, and hematological tumors, such as AML and MDS." (PMID 31681423, 2019). "IDH2, normally catalyzing the conversion of isocitrate to alpha-ketoglutarate in the Krebs cycle, is frequently mutated in hematopoietic neoplasms resulting in novel enzymatic activity producing 2-hydroxyglutarate (2-HG)." (PMID 29148847, 2018). "Enasidenib is a small molecule inhibiting mutant IDH2, which is overexpressed in hematological cancers: it has high selectivity, good solubility and oral bioavailability." (PMID 34065551, 2021).
metabolic disease (3 papers, 2018 to 2022). A congenital disorder (due to inherited enzyme abnormality) or acquired (due to failure of a metabolically important organ) disorder resulting from an abnormal metabolic process. "Histological analysis was performed to determine whether IDH2 deficiency induces metabolic disease." (PMID 36130994, 2022). "For the first time, we report our novel findings that IDH2 KO female mice may be more susceptible to fructose-induced NAFLD and the associated inflammatory response, suggesting a mechanistic role of IDH2 in metabolic diseases." (PMID 29861476, 2018). "To investigate the role of IDH2 in metabolic diseases characterized by tricarboxylic acid cycle (TCA) disorders, we compared the body weights of IDH2 KO and WT mice fed a normal diet (ND) or HFD." (PMID 36130994, 2022).
neurodegenerative disease (2 papers, 2025 to 2026). A disorder of the central nervous system characterized by gradual and progressive loss of neural tissue and neurologic function. "Identifying IDH2 as a target of CBN paves the way for future investigations into its role–and that of other TCA‐associated enzymes–in neurodegenerative diseases such as AD." (PMID 40388656, 2025).
cardiac disease (1 paper, 2021). "Notably, IDH1 and IDH2 mutations also occur as CHIP mutations and mechanistically lead to conversion of αKG to R-2HG, which is a proven oncometabolite and a potent inhibitor of TET2, suggesting a common pathway of CHIP induced cardiac disease." (PMID 32948843, 2021).
inflammation (1 paper, 2022). Aberrant reaction of the microcirculation characterized by movement of fluid and leukocytes from the blood into extravascular tissues. "Melatonin drives the circadian amplitude of mitochondrial isocitrate dehydrogenase 2 (Idh2) in adipose inflammation, and the gene clock regulates Idh2 at the transcription level." (PMID 36189281, 2022).
prostate (1 paper, 2022). "Elevated levels of RBP4 and cadherin-2 signal early stages of prostate carcinogenesis, while ENO1, T-kininogen 2 and IDH2 represent more advanced stages." (PMID 35886909, 2022).
IDH2 also shares sentences with these, for which no sentence is quoted: oligoastrocytoma (6 papers); bone tumour (3); diffuse large B-cell lymphoma (3); Enchondromatosis (3); acute lymphoblastic leukemia (2); adenoid cystic carcinoma (2); B-cell lymphoma (2); chordoma (2); chronic myeloid leukaemia (2); essential thrombocythemia (2); fibrosarcoma (2); gallbladder cancer (2); giant cell tumor (2); hereditary leiomyomatosis (2); invasive breast carcinoma (2); lung adenocarcinoma (2); malignant bone tumor (2); mental Retardation (2); mesenchymal tumors (2); nonalcoholic fatty liver disease (2); primary myelofibrosis (2); renal carcinoma (2); skin cancer (2); type 2 diabetes (2); uveal melanoma (2); acral lentiginous melanoma (1); acute kidney injury (1); acute leukemia (1); adenoma (1); adult acute myeloid leukemia (1).
A further 79 diseases each share a sentence with IDH2 in 1 paper.